PON1 (paraoxonase 1)
Diseases named in the same sentence as PON1 in open-access papers (continued):
Sharing a sentence is not in itself a finding about the gene and the disease.
morbid obesity (3 papers, 2019 to 2023). An excess of body weight, normally defined as an individual with a body mass index greater than 35 or a body weight greater than one hundred percent of ideal body weight. "Blood PON-1 arylesterase, paraoxonase, and lactonase activities were evaluated in patients with morbid obesity before and six months after Roux-en-Y Gastric Bypass (RYGB)." (PMID 31052559, 2019). "Many studies have shown that the serum activity of PON-1 in individuals suffering from several diseases (ischemia, chronic kidney disease, morbid obesity, dyslipidemia), the esterase activity of the enzyme is considerably reduced." (PMID 31052559, 2019). "Moreover, the differences were not substantial enough to identify PON1-related variables as biomarkers of NASH in morbid obesity." (PMID 38136158, 2023).
neuroblastoma (3 papers, 2023 to 2024). Neuroblastoma (NB) is the most common solid, extracranial childhood tumor. "Notably, Pon1 depletion caused changes in the Phf8- > H4K20me1- > mTOR- > autophagy pathway akin to the changes induced by HHcy in the mouse brain and neuroblastoma cells." (PMID 36899882, 2023). "The study showed that Pon1 depletion, which causes the accumulation of Hcy-thiolactone and the N-Hcy-protein in mice, downregulated the histone demethylase Phf8 and upregulated the H4K20me1 epigenetic mark in brains of Pon1−/− mice and in Pon1-silenced mouse neuroblastoma N2a-APPswe cells." (PMID 39125665, 2024). "To elucidate the mechanism by which Pon1 depletion impacts Phf8 and its downstream effects on mTOR, autophagy, and APP, we first examined whether the findings in Pon1−/− mice can be recapitulated in cultured mouse neuroblastoma N2a-APPswe cells that overproduce Aβ from a mutated human APP transgene." (PMID 36899882, 2023). "PON1 involvement in AD was examined using Pon1−/−5xFAD mice and in Aβ-overexpressing mouse neuroblastoma N2a-APPswe cells." (PMID 39594433, 2024). "Pon1 depletion downregulated Phf8 and upregulated Aβ in the brains of Pon1−/−5xFAD mice and in mouse neuroblastoma N2a-APPswe cells." (PMID 39125665, 2024). "Pon1 depletion by RNA interference or treatments with Hcy-thiolactone or N-Hcy-protein similarly elevated Aβ in mouse neuroblastoma cells." (PMID 39125665, 2024). "The depletion of Pon1 increased H4K20me1 binding to the mTOR promoter, demonstrated in mouse neuroblastoma N2a-APPswe cells, and upregulated mTOR signaling, which in turn inhibited the autophagy flux." (PMID 39125665, 2024). "In mouse neuroblastoma N2a-APPswe cells and in brains of Pon1−/−5xFAD mice, Pon1 depletion upregulated the amyloid precursor protein (App) and amyloid beta (Aβ)." (PMID 39125665, 2024). "In the present work, Pon1 depletion by RNA interference or treatments with Hcy-thiolactone or N-Hcy-protein similarly increased the accumulation of Aβ in mouse neuroblastoma cells." (PMID 36899882, 2023). "Although Pon1 depletion in mouse neuroblastoma N2a-APPswe cells downregulated Phf8 and upregulated APP and Aβ, depletion of Phf8 upregulated Aβ but not APP." (PMID 36899882, 2023). "Interestingly, we found that Pon1 depletion upregulated mTOR signaling and inhibited autophagy via Pcft/H4K20me1 in mouse brain and neuroblastoma cells, suggesting that effects of Pon1 depletion on gene expression are disease/tissue-specific." (PMID 39594433, 2024). "Specifically, we found that Pon1 depletion downregulated histone demethylase Phf8 both at the protein and mRNA level, increased H4K20me1 binding at the mTOR promotor, and upregulated mTOR expression and phosphorylation in the mouse brain and neuroblastoma N2a-APPswe cells." (PMID 36899882, 2023). "In the present study, we found that depletion of Pon1 upregulated APP in the Pon1−/−5xFAD mouse brain and in mouse neuroblastoma N2a-APPswe cells." (PMID 36899882, 2023).
obstructive sleep apnea (3 papers, 2014 to 2024). "Similar to our current results, obese patients displaying obstructive sleep apnea showed reduced serum PON-1 activities with elevated oxLDL levels, inflammation, and endothelia dysfunction." (PMID 30072955, 2018).
organophosphate poisoning (3 papers, 2011 to 2017). Poisoning due to organophosphates (a class of organophosphorus compounds also known as phosphate esters, or OPEs). "This study was conducted to evaluate the effect of prolonged resveratrol intake on paraoxonase-1 levels in rats, and its role as a potential prophylactic treatment in organophosphate poisoning." (PMID 28265445, 2016). "In vitro findings suggest that the phytoalexin resveratrol can elevate paraoxonase-1 levels and thus may provide protection against organophosphate poisoning." (PMID 28265445, 2016).
osteoarthritis (3 papers, 2019 to 2022). A noninflammatory degenerative joint disease occurring chiefly in older persons, characterized by degeneration of the articular cartilage, hypertrophy of bone at the margins and changes in the synovial membrane. "A previous study found that the RS1501299 polymorphism of the Adipoq increases the risk of knee osteoarthritis, and the interaction between the rs1501299 (Adipoq) and rs662 (Pon1) gene polymorphisms may play an important role in the development of osteoarthritis." (PMID 36276964, 2022). "The previous study found that SNP rs182052 is significantly associated with susceptibility to knee osteoarthritis in the Chinese population, and the interaction between rs1501299 (ADIPOQ) and rs662 (PON1) gene polymorphisms may play an important role in the development of osteoarthritis." (PMID 31139654, 2019). "In conclusion, post-op oral HA administration in canine patients with CCL injury leads to improvements in osteoarthritis biomarkers, namely higher synovial fluid HA concentrations and reduced synovial fluid paraoxonase-1 concentrations." (PMID 33925642, 2021).
pancreatitis (3 papers, 2020 to 2025). Inflammation of the pancreas. "In the first one, the values of CRP and ferritin, together with the other three APPs that are include in our profiles (i.e., Hp, albumin and PON-1) in dogs with pyometra were compared with healthy dogs and with dogs suffering from another inflammatory condition such as pancreatitis." (PMID 37344860, 2023). "Dogs with pyometra and pancreatitis showed statistically significantly higher serum CRP and Hp and lower serum PON-1 and albumin concentrations when compared with healthy dogs." (PMID 37344860, 2023). "Additional studies have explored PON-1 alterations in babesiosis, ehrlichiosis, parvoviral and non-specific enteritis, sepsis, pancreatitis, atopic dermatitis, cardiac diseases, and hypercortisolism." (PMID 41295705, 2025).
papillary thyroid cancer (3 papers, 2017 to 2025). "For example, decreased serum PON1 activity and increased levels of lipid peroxidation have been reported in 45 Pakistani patients with oral squamous cell carcinoma, and 30 Turkish patients with esophageal squamous cell carcinoma, and a further 25 Turkish patients with papillary thyroid cancer." (PMID 29176871, 2017). "Another study reported increased PON1 and ARE activity compared to preoperative levels in patients with papillary thyroid cancer and undergoing total thyroidectomy." (PMID 32549522, 2020).
periodontitis (3 papers, 2019 to 2024). An acute or chronic inflammatory process that affects the tissues that surround and support the teeth. "Among the AgP-related suggestive genes, we selected the genes which have been reported to be associated with periodontitis and are expressed in the periodontal tissue, and found two genes, sphingomyelin phosphodiesterase 3 (SMPD3) and paraoxonase-1 (PON-1)." (PMID 39917667, 2024). "The results of a previous study showed that carriers of the SNP rs854560 PON-1 have a high rate of moderate periodontitis." (PMID 39917667, 2024). "Besides PON-1 and SMPD3, there have been no reports directly showing the association between the identified genes and periodontitis." (PMID 39917667, 2024).
renal cell carcinoma (3 papers, 2019 to 2020). "The methylation status of different genes in renal cell carcinoma samples was obtained by CpG islands arrays and hypermethylated PON1 was selected for further study." (PMID 31400051, 2019). "PON1 was down‐regulated in renal cell carcinoma tissues detected by qRT‐PCR and Western blot." (PMID 31400051, 2019).
small cell lung carcinoma (3 papers, 2017 to 2026). Small cell lung cancer (SCLC) is a highly aggressive malignant neoplasm, accounting for 10-15% of lung cancer cases, characterized byrapid growth, and early metastasis. "This commentary discusses the prognostic relevance of leukocyte telomere length and paraoxonase-1 activity in small-cell lung cancer (SCLC) patients undergoing chemotherapy." (PMID 41399661, 2026). "Our study emphasizes the prognostic significance of LTL and PON1 activity in small-cell lung cancer." (PMID 40469570, 2025). "Our group previously demonstrated that post-translational modification of serum PON1 in form of fucosylated PON1 is a potential biomarker of small cell lung cancer." (PMID 28467805, 2017).
ST Elevation Myocardial Infarction (3 papers, 2016 to 2024). A myocardial infarction that produces elevation in the ST segments of the ECG. "Therefore the aim of our study was to investigate the association of rs662 and rs854560 SNPs of the PON1 gene with 5-year overall mortality in patients with ST-elevation myocardial infarction (STEMI)." (PMID 25155309, 2016).
viral infections (3 papers, 2021 to 2025). "Despite the growing interest in these antioxidant strategies, the therapeutic modulation of PON1 in viral infections remains largely unexplored." (PMID 40723899, 2025). "Despite PON1’s antioxidant, anti-inflammatory, and lipid oxidation-reducing activities, little is known about its role in virus infection." (PMID 35746674, 2022). "Interestingly, increasing evidence suggests that PON1 activity is involved in virus infection, including influenza A virus, hepatitis C virus (HCV), hepatitis B virus (HBV), human immunodeficiency virus (HIV), SARS-CoV-2, and others." (PMID 35746674, 2022). "However, little is known of PON1 in porcine, especially during virus infection." (PMID 35746674, 2022).
Abdominal obesity (2 papers, 2019 to 2020). Excessive fat around the stomach and abdomen. "This seems to favour abdominal obesity associated to high values of proinflammatory interleukin 6, which, however, is not correlated with a lower activity of the oxidation marker PON1." (PMID 32168955, 2020). "Taking this into account, the aim of this study is to analyse the eating habits related to calorie intake and its impact on the abdominal obesity associated with anthropometric variables, PON1 activity and IL-6 levels in serum." (PMID 32168955, 2020). "The aim of this study was to analyse the eating habits related to calorie intake and their impact on abdominal obesity associated with anthropometric variables, the activity of the oxidation marker paraoxonase 1 (PON1), and interleukin 6 (IL-6) levelsin MS patients." (PMID 32168955, 2020). "The aim of this study was to evaluate the influence of sex on serum paraoxonase-1 (PON1) activities and on its relationship with cardiovascular disease risk factors such as overall and central obesity." (PMID 31138960, 2019). "This seems to favour the abdominal obesity associated with high values of proinflammatory IL-6 that is not correlated with a lower activity of PON1." (PMID 32168955, 2020).
age-related macular degeneration (2 papers, 2013 to 2021). Age-related loss of vision in the central portion of the retina (macula), secondary to retinal degeneration. "Paraoxonase-1 activity is associated with age-related macular degeneration.Two polymorphisms (L55M and Q192R) were shown to increase paraoxonase-1activity and have been implicated in the development of age-related maculardegeneration." (PMID 33567022, 2021).
alcoholic fatty liver disease (2 papers, 2021 to 2023). Lipid infiltration of the hepatic parenchymal cells that is due to alcohol abuse. "This study investigated PON1 activities and concentrations in morbidly obese individuals and explored the impacts of the genetic polymorphism PON1 rs662 and non-alcoholic fatty liver disease on enzymatic properties." (PMID 38136158, 2023).
arteriosclerosis (2 papers, 2012 to 2013). A vascular disorder characterized by thickening and hardening of the walls of the arteries. "A close relationship between PON-1 deficiency and accelerated progression of arteriosclerosis has been found in experimental and human studies." (PMID 22291696, 2012).
artery disease (2 papers, 2019 to 2021). "The variants c.1936A>G on AKAP10 and c.575A>G on PON1 are linked to defects in cardiac conduction and artery disease, respectively." (PMID 33466296, 2021). "Epidemiological and cohort studies provided convincing evidence on the protective paper of PON-1 against artery disease, through its ability to prevent lipid oxidation and limit the development of atherosclerotic lesion due to its connection with HDL." (PMID 30660196, 2019).
astrocytoma (2 papers, 2010 to 2023). "For astrocytoma patients the results for association tests for the PON1 L55M polymorphism were as follows: Genotypic test, p = 0.989; trend test, p = 0.886, dominant model, p = 0.884, recessive model p = 0.932." (PMID 20723250, 2010).
autoimmune (2 papers, 2018 to 2024). "Impaired high-density lipoprotein (HDL) levels and antioxidant functionality of HDL, mainly attributed to a decreased paraoxonase-1 (PON1) functionality, have been described in autoimmune conditions." (PMID 29740582, 2018).
autoimmune disease (2 papers, 2018 to 2023). A disorder resulting from loss of function or tissue destruction of an organ or multiple organs, arising from humoral or cellular immune responses of the individual to their own tissue constituents. "Altered DNA methylation of genes, such as, PON1, ADARB2, USP16, UHMK1, and DISC1, was previously reported to be related to cancer or autoimmune diseases." (PMID 37744384, 2023).
B-cell lymphoma (2 papers, 2013 to 2015). "Despite the fact that further confirmation is needed, this study shows that the PON1 GG genotype in rs662 polymorphism could be a risk factor for B-cell lymphomas." (PMID 23651475, 2013).
breast tumor (2 papers, 2009 to 2011). "It was, therefore, aim of the present study also to analyze the relationships of PON1 allelic variants with the risk of BC and to clarify the question whether both gene variations might be useful genetic markers of breast tumor." (PMID 19379515, 2009). "In particular, loss of the paraoxonase 1 care-take function could play an important role in increasing the breast vulnerability to genomic damage caused by inflammatory oxidants, dietary carcinogens, as well as in estrogen-lipidic metabolism, that may modulate the progression of breast tumor." (PMID 19379515, 2009). "Using this protein in prevention of poisoning (e.g. in chemical warfare) may have serious implications, such as breast tumor development, should at the time of high PON1 levels, IL6 levels also be raised." (PMID 21711799, 2011).
bronchiectasis (2 papers, 2020 to 2023). Segmental, irreversible dilation of the bronchial tree resulting in the accumulation of secretions which leads to obstruction. "Trends for an association of lower baseline PON1 activities (p > 0.05) and significantly higher levels of LTB4, and 13-HODE (p < 0.05) were noted in patients with bronchiectasis compared to patients without bronchiectasis on longitudinal CT." (PMID 36138190, 2023).
cardiac ischemia (2 papers, 2012 to 2015). "The results of the present study suggested that the PON1 R and M alleles may play a role in the pathogenesis of cardiac ischemia in our North African population." (PMID 26241956, 2015). "We then assessed the mean plasma levels of C-reactive protein and myocardial ischemia markers (troponin I, CK-MB, and myoglobin) according to the PON1 55 carriers." (PMID 22536511, 2012).
celiac disease (2 papers, 2012 to 2018). An autoimmune genetic disorder with an unknown pattern of inheritance that primarily affects the digestive tract. "In conclusion, our results confirm that celiac disease is associated with oxidative damage and with significant decrease of PON1 activities." (PMID 22536510, 2012). "Interest in the study of PON1 in celiac disease is supported by recent studies that have suggested a possible role of PON1 in inflammatory intestinal diseases." (PMID 22536510, 2012). "Aim of the study was to investigate the alteration of paraoxonase-1 activity in celiac disease (CD), an intestinal disorder characterized by toxic injury exerted by gluten peptides." (PMID 22536510, 2012). "Although a decrease of paraoxonase-1 activity and an increase of lipid peroxidation products are not specific of celiac disease, they could exert a proinflammatory and cytotoxic effect and could therefore contribute to gastrointestinal cell injury in CD." (PMID 22536510, 2012).
cognitive decline (2 papers, 2023 to 2025). "Genetic analysis revealed a significant association between cognitive decline and polymorphisms in the ACE and PON1 genes." (PMID 40283626, 2025).
colitis (2 papers, 2016 to 2025). Inflammation of the colon. "The novel marker paraoxonase‐1 (PON‐1) decreases during inflammation and oxidative stress, and its serum activity was therefore investigated in horses with colitis to assess its diagnostic and prognostic capacity." (PMID 39836076, 2025). "Clinical relevance: PON‐1 seems to add little to existing markers as it had suboptimal diagnostic performance and little prognostic abilities in horses with colitis." (PMID 39836076, 2025). "PON‐1 activity correlated only weakly with known inflammatory markers and disease severity markers and does not appear to reflect the clinical status of horses with colitis." (PMID 39836076, 2025).
dilated cardiomyopathy (2 papers, 2023). Cardiomyopathy which is characterized by dilation and contractile dysfunction of the left and right ventricles. "In other studies, stage D dogs had lower PON-1 activity when compared to stages A and B, but both MVD and dilated cardiomyopathy patients were included." (PMID 36669034, 2023).
epilepsy (2 papers, 2022 to 2026). A brain disorder characterized by episodes of abnormally increased neuronal discharge resulting in transient episodes of sensory or motor neurological dysfunction, or psychic dysfunction. "Phrased differently, the results show that lowered antioxidant potential, which is in part determined by the Q192R PON1 variants and lowered -SH groups, coupled with increased aldehyde formation are a key part of the TLE-PP phenome of epilepsy." (PMID 35624666, 2022). "PLS Smart was used to analyze the multi-step, multiple mediation relationships between input factors (Q192R PON1 genotype, CMPAase activity, other antioxidants, oxidative stress biomarkers) and the output variables, namely severity of epilepsy and comorbid psychiatric disease." (PMID 35624666, 2022).
esophageal squamous cell carcinoma (2 papers, 2017 to 2021). Esophageal squamous cell carcinoma (ESCC) is a type of esophageal carcinoma (EC) that can affect any part of the esophagus, but is usually located in the upper or middle third. "In esophageal squamous cell carcinoma, increased oxidative stress is associated with decreased antioxidant PON1 activities." (PMID 34439311, 2021).
falciparum malaria (2 papers, 2010 to 2012). "Interestingly, human serum paraoxonase (PON1) an HDL-associated esterase which protects lipoproteins against oxidation, found to be down-regulated in falciparum malaria patients." (PMID 22912677, 2012). "Decreased serum PON-1 activity in context with falciparum malaria may in part be attributable to higher SAA level." (PMID 22912677, 2012).